XIST (X inactive specific transcript)
Diseases named in the same sentence as XIST in open-access papers (continued):
Sharing a sentence is not in itself a finding about the gene and the disease.
tumor (continued). "Differential expression analysis revealed significant divergence in lncRNA profile between parental tumors and tumor-derived cell cultures in vitro, including the following particles: MALAT1, CASC2, H19, TUSC7, XIST, RP11-838N2.4, DLX6-AS1, GLIDR, MIR210HG, SOX2-OT." (PMID 33245508, 2022). "Recently, complex lncRNA/miRNA/mRNA networks based on XIST/miR-500a-3p, miR-370-3p, miR-2467-3p, miR-512-3p/XBP have been demonstrated to promote cell proliferation and aggravated tumor growth in vivo by regulating endoplasmic reticulum stress response and cell apoptosis." (PMID 35054794, 2022). "Downregulation of XIST was observed in HCC cells and tumor specimens." (PMID 35723009, 2022). "LncRNAs such as MALAT1, XIST and NORAD have been proven to be biomarkers for human tumor prognosis." (PMID 35183058, 2022). "Additionally, XIST also promoted EMT and tumor stemness via regulating the miR-133a/SOX4 and miR-152-Krüppel-like factor 4 (KLF4) axes, respectively." (PMID 34322395, 2021). "XIST was specifically expressed in female GIST patients and was dramatically down-regulated in G3/G4 subtypes, which suggested XIST was significantly inhibited during tumor progression and it seemed to have a protective effect in female GIST patients." (PMID 34557343, 2021). "We assumed that the lncRNA XIST played a tumor suppressor role in OSCC, due to a lack of expression increasing the morbidity." (PMID 34640640, 2021). "Downregulation of XIST resulted in activation of c-Met and induction of the EMT, which resulted in increased secretion of exosomal miRNA-503 and suppression of T-cell proliferation, and promoted stemness of tumor cells." (PMID 32219093, 2020). "The CCK-8 assay results showed that IC50 of anti-tumor drug doxorubicin on KG-1 cells was decreased, and drug-resistant proteins MRP1 and P-GP showed down-regulated expression after silencing XIST, which was rescued by overexpression of MYC (all p < 0.05)." (PMID 33228517, 2020). "They revealed that XIST acts as a ceRNA for miR-34a via sponging miR-34a, competing with hepatocyte growth factor receptor (MET) for miR-34a binding, and decreasing ATC cell lines proliferation in vitro and tumor growth in vivo." (PMID 32760219, 2020). "Clustering of tumour and healthy lung samples in a 2D map using t-SNE algorithm based on the normalized expression levels of XIST, TSIX, hnRNPu, Bcl-2, and BRCA1, revealed that collectively these five genes -when assessed together- can have a diagnostic potential in both LUAD and LUSC." (PMID 33255394, 2020). "Furthermore, while both high-XIST systems have miRNA-DMX relationships that decrease when compared to the low-XIST tumours, the miRNA-DMX relationships are stronger in males with elevated XIST (n = 12) than in females with comparable XIST expression." (PMID 31419261, 2019). "In breast cancer, XIST acts as a tumor suppressor by positively regulating the expression of non-X-chromosome gene PH domain and leucine rich repeat protein phosphatase 1 (PHLPP1), which in turn catalyzes dephosphorylation of protein kinase B (AKT)." (PMID 30654440, 2019). "For example, by interacting with miRNAs, several lncRNAs (including GAS5, XIST, NORAD, and Linc00511) modulate PC progression by enhancing the proliferation, migration and invasive capacity and angiogenesis of PC cells as well as tumor growth in vivo." (PMID 31488171, 2019). "And there was a lack of systematic research for effect of lncRNA XIST expression on tumor prognosis." (PMID 29556138, 2018). "Transformed cell lines showed variable effects following SAF-A knockdown, but none had so clear and pronounced an effect on XIST RNA localization as in the Neuro 2A tumour cell line." (PMID 28947659, 2017).
tumor (continued). "In the present study, we found that XIST was overexpressed in tumor tissues compared with that in normal counterparts and correlated with poor prognosis." (PMID 29100288, 2017). "Furthermore, our data provided the first evidence that XIST functions as a molecular sponge for miR-101 and EZH2 and knockdown of XIST exerted tumor-suppressive functions in human ESCC by epigenetic regulation of EZH2 via reciprocal repression of miR-101." (PMID 29100288, 2017). "These tumor suppressive effects do not rely directly upon the effects of XIST but on miR-152, which is released from its interaction with XIST." (PMID 26992233, 2016). "Interestingly, the expression level of XIST was also decreased in EAC and correlated with tumor grade." (PMID 25286960, 2014). "To further explore whether targeting the NAT10/XIST/YAP1 axis augments the antitumor effect of immune checkpoint inhibitors (ICIs), we administered Remodelin, Verteporfin, and an anti-PD-1 monoclonal antibody to tumor-bearing mice." (PMID 40860183, 2025). "A previous study demonstrated that XIST promotes transforming growth factor-beta (TGF-β)-induced EMT which may regulate the miR-367/miR-141-ZEB2 axis in NSCLC, and our results showed that ZEB2 was highly expressed in the XIST+ tumor cells." (PMID 37430270, 2023). "Downregulation of lncRNA XIST activated three distinct pathways, epithelial-mesenchymal transition (EMT), MSN/c-Met, and release of exosomal miR-503, thus knockout of XIST in mice mammary glands promoted the primary tumor growth as well as metastasis in the brain." (PMID 34707990, 2021). "The overexpression of miR‐125b‐2‐3p slowed tumor growth and increased drug sensitivity; moreover, knocking down WEE1 further slowed growth and promoted drug sensitivity, finally when miR‐125b‐2‐3p was overexpressed, lncRNA XIST was knocked down and WEE1 knocked down simultaneously." (PMID 33666372, 2021). "Without XIST in tumor cells, the mice exhibited better survival." (PMID 33364236, 2020). "However, FSTL1+ tumor cells, which were most abundant in the PD-1+SMI group, expressed high levels of the lung CSCs marker genes CD44 and ALCAM, and the CSCs score was significantly higher than those in the other subclusters, except for NEAT1+ and XIST+ tumor cells." (PMID 37430270, 2023). "Notably, following DOX withdrawal after week 11, SUM159_shXIST tumor cells resumed rapid tumor growth, suggesting that DOX-induced XIST KD did not kill SUM59 tumor cells, but rather impaired their growth." (PMID 36922677, 2023).
cancer (204 papers, 2009 to 2026). A tumor composed of atypical neoplastic, often pleomorphic cells that invade other tissues. "Inhibitors of XIST expression and activity are in active development for applications in X-linked inherited diseases and cancer." (PMID 41601966, 2026). "Previous studies have indicated that dysregulation of XIST is associated with the progression of various cancers." (PMID 40308577, 2025). "Marker genes that were highly expressed in this group of cells include the cancer-associated imprinted genes XIST, NEAT1, and MEG3." (PMID 40585258, 2025). "MUC1-C and XIST have been linked to the regulation of diverse miRNAs associated with cancer progression." (PMID 38740827, 2024). "Studies in female and male cancer cells have indicated that XIST overexpression is associated with transcription of the active X chromosome." (PMID 38740827, 2024). "Our results suggest that XIST plays a critical role in ovarian CSCs and that loss of XIST unlocks cell stemness and plasticity in cancer cells." (PMID 39546568, 2024). "It is consistent with the developmental role of XIST depletion during reprogramming and iPSC process that XIST loss in cancer cells leads to an enrichment of CSCs." (PMID 39546568, 2024). "The loss of XIST can trigger X chromosome reactivation, leading to overexpression of X-linked genes, which causes cancer progression." (PMID 39546568, 2024). "Additional examples and evidence are required to better understand how XIST regulates cancer cells and how it affects cancer susceptibility, especially in cancers that predominantly affect women." (PMID 39546568, 2024). "To examine molecular features, we performed GSEA on the OVCAR3-KRAB transcriptome profiles to identify the mesenchymal-like cancer SC signature associated with XIST expression." (PMID 39546568, 2024). "Dysregulation of XIST expression has been recognized across numerous female and male cancers in association with both tumor progression and suppression." (PMID 38740827, 2024). "Another potentially targeted lncRNA was XIST (X-inactive specific transcript), an extensively studied lncRNA associated with several cancer pathologies due to its ability to mediate post-transcriptional gene silencing." (PMID 37834197, 2023). "Only 4 miRNAs, including miR-103a-3p, miR-107, miR-130b-3p and miR-96–5p, were negatively linked with XIST in more than 3 types of cancers." (PMID 36212008, 2022). "Another study demonstrated that XIST depletion leads to a decreased cancer cell proliferation associated with a reduction in MET protein levels through sponging miR-34a, which is able to inhibit MET protein synthesis." (PMID 35804851, 2022). "In recent years, lncRNA XIST has been reported to be strongly associated with the development and progression of cancers." (PMID 33666372, 2021). "Many studies have demonstrated the aberrant expression of XIST in cancer cells and tissues, and revealed the association of XIST with tumorigenesis, metastasis, and cell apoptosis." (PMID 34771549, 2021). "XIST has both diagnostic and prognostic values in different cancers, albeit the prognostic value of this lncRNA has been more validated." (PMID 34179019, 2021). "These apparent bifunctional roles of XIST in cancer underscores the importance of understanding the molecular mechanisms underlying XIST function in determining when and where targeting XIST would be clinically beneficial." (PMID 29732012, 2018). "Our results suggested that high expression levels of XIST were associated with unfavorable overall survival in cancer patients (pooled HR = 1.81, 95% CI: 1.45–2.26)." (PMID 29752340, 2018). "In this study, high expression of lncRNA XIST in cancer tissue was associated with poor prognosis in cancer patients (HR = 1.54, 95% CI 1.07–2.23, p = 0.021), with heterogeneity in the data (I2 > 50%)." (PMID 29556138, 2018). "In summary, our results suggest that abnormal XIST expression in human cancer is associated with OS and DFS of patients." (PMID 29568404, 2018).
cancer (continued). "Hazards ratios (HRs) with corresponding 95% confidence intervals (CIs) were pooled to estimate the association between lncRNA XIST expression and survival of cancer patients from Asian." (PMID 29556138, 2018). "In conclusion, the high expression of lncRNA XIST was a close associate to the poor prognosis of cancer patients." (PMID 29556138, 2018). "In vitro downregulation or upregulation of XIST was associated with altered cell proliferation, metastasis, and apoptosis in several cancer models." (PMID 29147648, 2017). "Dysregulated expression of XIST was associated with initiation, progression and metastasis of several cancers." (PMID 29100288, 2017). "Typically, only one active X-chromosome is present in human cells, but in human cancers, a loss of a normal X-chromosome can be observed along with dysregulated XIST expression." (PMID 27608009, 2016). "Deregulation of XIST leads to loss or gain of X chromosomes resulting in a variety of female, male and non sex specific cancers, demonstrating the participation of lncRNAs in maintaining genomic stability." (PMID 26082843, 2015). "Not only in male and female cancers, XIST is implicated in sex independent cancers as well, mainly in lymphomas and leukemias." (PMID 26082843, 2015). "The loss of XCI and the down-regulation of XIST expression are frequently associated with cancers, but this association is strictly correlative." (PMID 23875687, 2013). "A recent work demonstrated that the loss of XIST results in X chromosome reactivation and can cause haematopoietic cancers in mice, presenting a direct link between X chromosome and cancer." (PMID 23875687, 2013). "XIST loss in cancer cells may be subject to an altered epigenetic profile that modifies transcriptional control of X-linked genes." (PMID 40981384, 2025). "Among common miRNAs identified in in the RNA-seq datasets, we confirmed that MUC1-C and XIST are necessary for expression of miR-21, which was of interest in that miR-21 is overexpressed across pan-cancers and is associated with the regulation of NF-κB and inflammation." (PMID 38740827, 2024). "XIST dispersion was associated with cancer cells growth, particularly in breast cancer." (PMID 39639337, 2024). "In researching why the loss of XIST distorts cancer cells’ oxidative stress control, they have found that it can act as a sponge for miR-335, inducing an increase in SOD2 expression, a crucial enzyme in the antioxidant process of cells, transforming •O2− to H2O2." (PMID 36077530, 2022). "XIST is responsible for silencing several genes, and the observation that the X-linked oncogenes ARAF-1 and ETS-like 1 (ELK-1) are overexpressed in tumors with multiple active X chromosomes suggests that the deregulation of XIST may be associated with cancer." (PMID 33916248, 2021). "XIST loss may result in X reactivation and consequent genome-wide changes that lead to cancer, indicating that XIST RNA was required to maintain XCI and to suppress cancer in vivo." (PMID 31467637, 2019). "Furthermore, in human cancers a deregulation of XIST expression along with the loss of the normal X chromosome has been observed." (PMID 29732012, 2018). "It has been proposed that the down-regulation of XIST acts as an underlying mechanism for the up-regulation of X-linked inhibitor of apoptosis and the prevention of drug-induced apoptosis, which leads to resistance phenotype in cancer cells." (PMID 27664137, 2017). "Previous studies reported that XIST is associated with cancers through regulating miRNA." (PMID 29371940, 2017). "As epithelial mesenchymal transition (EMT) initiated metastasis constitutes the major cause of cancer related death, we therefore proceed to test whether XIST was involved in EMT of ESCC cells." (PMID 29100288, 2017). "Whether XIST interacts with BRCA1 to regulate cancer progression or if genetic instability due to loss of BRCA1 expression is responsible for reduced XIST expression is yet to be clarified." (PMID 25400658, 2014).
cancer (continued). "Moreover, the significant higher levels of XIST-RNA detected in BRCA1-associated respect to sporadic basal-like cancers, opens the possibility to use XIST expression as a marker to discriminate between the two groups of tumors." (PMID 19440381, 2009). "However, XIST was linked to poor outcomes for cancers of HNSC, KIRC, KIRP, LIHC and PAAD." (PMID 36212008, 2022). "The expression of XIST has been shown to fluctuate in cancer cells, drawing attention to the intricate and contentious function it plays in cancer biology." (PMID 41459628, 2026). "sEVs also modulate lipid metabolism in cancer by upregulating X-inactive specific transcript (XIST), which suppresses miR-655 and activates downstream signaling pathways that increase ATP citrate lyase (ACLY) expression." (PMID 41322698, 2025). "Given the epigenetic mechanisms of gene regulation that TSIX and XIST play in immune cells, their dysregulation can affect NK cell activities in cancer patients, such as NK cell cytotoxicity and cytokine release." (PMID 40781182, 2025). "Altogether, our studies provide insight into how cysteine 328 in vimentin dictates mechano-transduction signals to remodel actin cytoskeleton and protect against EMT and cancer growth via modulating lncRNA XIST." (PMID 40690373, 2025). "A mounting body of evidence demonstrates XIST involvement in different human cancers as both a tumor suppressor gene, and an oncogene." (PMID 39639337, 2024). "The present results demonstrate that MUC1-C upregulates XIST expression in male and female cancer cells." (PMID 38740827, 2024). "Aberrant overexpression of XIST in cancer largely functions in promoting oncogenesis by regulating inflammation and diverse miRNAs that contribute to the CSC state and drug resistance." (PMID 38740827, 2024). "Recent developments revealed significant crosstalk of XIST, via a range of miRNAs, with proteins that affect the pathological mechanisms of cancer and cardiovascular diseases including PAH." (PMID 39639337, 2024). "In support of this MUC1-C/XIST auto-inductive pathway, we show that MUC1-C and XIST regulate common sets of genes associated with chronic inflammation and cancer progression." (PMID 38740827, 2024). "We also found that the MUC1-C/XIST pathway regulates expression of the NEAT1 and MALAT1 lncRNAs, which have been linked to inflammation and cancer progression." (PMID 38740827, 2024). "In contrast to samples with high XIST expression, samples with low XIST expression showed a higher mRNA stemness index, suggesting the presence of more cancer SCs in tumors with low XIST expression." (PMID 39546568, 2024). "Of significance, MUC1-C and XIST regulate common genes associated with inflammation and stemness, including (i) miR-21 which is upregulated across pan-cancers, and (ii) TDP-43 which associates with the XIST E repeats." (PMID 38740827, 2024). "Many recent studies confirmed XIST participation in a substantial number of pathologies like neurological, cardiovascular, lung, kidney, pancreas, skin, autoimmune, bone diseases and cancers." (PMID 39639337, 2024). "In contrast to studies of XCI, less is known about the regulation of XIST, the effectors that bind to the XIST array repeats and downstream target genes in cancer cells." (PMID 38740827, 2024). "Upregulation of XIST was reported to be associated with overexpression of EZH2, a key component of PRC2, and to act as an adverse prognosis indicator of cancer in male and female patients." (PMID 39639337, 2024). "The present studies demonstrate that MUC1-C increases XIST expression in male and female cancer cells." (PMID 38740827, 2024). "GSEA also uncovered that MUC1-C and XIST regulate the MIR146A TARGETS gene signature, which like miR-21, miR-146a associates with inflammation and cancer." (PMID 38740827, 2024).